TLR9 (toll like receptor 9)
Diseases named in the same sentence as TLR9 in open-access papers (continued):
Sharing a sentence is not in itself a finding about the gene and the disease.
asthma (45 papers, 2007 to 2025). "Regarding asthma, TLR2, TLR4, TLR7, TLR8, and TLR9 polymorphisms have been elucidated by their implication in allergic and asthma pathways and are also related to allergic and asthma exacerbations." (PMID 37920579, 2023). "In a study of Tunisian children, SNPs in TLR9 were reported to play a role in the predisposition to asthma and were also associated with asthma risk in a recent meta-study." (PMID 28228119, 2017). "With respect to TLR-9 SNPs, the -1237T/C polymorphism has been shown to be associated with asthma, Crohn's disease and HIV infection." (PMID 23472199, 2013). "Our group and others have previously reported an association between a single nucleotide polymorphism (SNP) in the promoter region of TLR9 (rs5743836 or -1237C/T) and asthma in European American adults and Tunisian children." (PMID 21324137, 2011). "So far, the most studied TLR9 SNP (C-1237T), which has been linked to asthma, is located within the promoter region of the TLR9 gene." (PMID 19924287, 2009). "When exploring the biological impact of other genes mapped to the dmCpGs uniquely associated with father’s pubertal smoking, several were related to genes associated with innate immunity, allergic diseases and asthma development, such as TLR9, CSF1R, DNAJ14, NTRK2 and TPCN1." (PMID 37649101, 2023). "Interestingly, TLR9(T1237C) was strongly associated with asthma among European-Americans, yet correlated poorly with asthma among Japanese." (PMID 26361369, 2015). "Additionally, genetic factors play a role, as specific TLR9 polymorphisms may influence the clinical manifestations of childhood asthma." (PMID 40672946, 2025). "This was evaluated in in vivo models where TLR9 activation was found to be associated with a reduction in antigen-induced respiratory allergic responses, suggesting that TLR9 ligands could be used as prophylactic and therapeutic agents in asthma." (PMID 27274620, 2016). "In addition, SNPs in the TLR9 gene were associated with increased risk of asthma." (PMID 23781124, 2013). "The CC genotype of TLR9 and the GG genotype of TLR10 are associated with better asthma control and better cardiac function." (PMID 40218167, 2025). "TLR9 and TLR10 were linked to better asthma control and improved cardiac function, while subclinical left and right ventricular dysfunction was observed in asthmatic children." (PMID 40218167, 2025). "Here, we co‐cultured the ISS with HEK‐Blue hTLR9 cells and observed a more pronounced activation of TLR9 in cells cultured with ISS from asthma patients." (PMID 39950864, 2025). "The expression levels of IL17RA, IL4RA, integrin β2, CCR3, FCER1A, TGFB1, TLR‐3, TLR‐7, and TLR‐9 in eosinophils treated with IL‐17 for 3 h were higher for normal individuals than for patients with asthma." (PMID 39575691, 2024). "Single nucleotide polymorphisms (SNP) in five different TLRs (TLR2, TLR4, TLR6, TLR9, TLR10) were described to significantly contribute to asthma susceptibility, severity, and responsiveness." (PMID 37759430, 2023). "In a population of Tunisian children, polymorphisms in TLR9 and CD14 were associated with a predisposition for asthma and atopy." (PMID 37426425, 2023). "A TLR9 agonist shows the capacity to restore the Th2/Th1 imbalance in asthma by inducing type 1 responses." (PMID 36366542, 2022). "First, to evaluate the role of TLR9 in HDM-induced allergic asthma, we induced this asthma in WT mice and Tlr9−/− mice." (PMID 33093516, 2020). "The mechanism of the asthma-suppressive effect in Tlr9−/− mice relied on the over-induction of IL-17A, creating a situation of Th17 activation that antagonized Th2 inflammation." (PMID 33093516, 2020). "The modulation of p75NTR on pDCs significantly influences disease progression of asthma in an ovalbumin-induced mouse model mediated by the TLR9 signaling pathway." (PMID 28861085, 2017). "TLR9 is also involved in the inhibition of airway remodeling, suggesting a potential protective role of TLR9 in asthma." (PMID 27274620, 2016).
asthma (continued). "Understanding of the TLR9 signal cascade has prompted the clinical development of TLR9 agonists to treat cancer as well as infectious diseases, asthma, and allergies." (PMID 25971982, 2015). "This chronic model is steroid insensitive and less sensitive to therapeutic intervention with the TLR7 and TLR9 agonist resiquimod or CpG-ODN than other published severe asthma models." (PMID 24618687, 2014). "We chose to use dexamethasone, TLR7 (resiquimod; R848) and TLR9 (CpG-ODN) agonists because all three have been previously shown to have potent anti-allergic effects in animal models of asthma." (PMID 24618687, 2014). "TLR9 is one of the most extensively studied TLRs in asthma, and it is currently thought to modulate allergic responses by skewing the balance from a Th2 towards a Th1 response." (PMID 23781124, 2013). "Synthetic immunostimulatory sequence oligodeoxynucleotides (ISS-ODNs) activate TLR9 and are more effective than steroids in attenuating the hypersensitivity response of asthma, allergic conjunctivitis, and allergic rhinitis." (PMID 22577387, 2012). "Prior studies suggest a role for a variant (rs5743836) in the promoter of toll-like receptor 9 (TLR9) in asthma and other inflammatory diseases." (PMID 21324137, 2011). "These compounds can potentially be used in infectious diseases, allergy/asthma and cancer therapy to either block TLR9 self-recognition or stimulate the immune response in conditions of immune tolerance." (PMID 22132241, 2011). "Treatment with TLR9 agonists inhibited the development of airway hyperresponsiveness, mucus production, and airway eosinophil infiltration in mouse asthma models." (PMID 18315834, 2008). "In murine models of asthma and allergy, TLR9 stimulation with CpG during as well as after the sensitization procedure, appears to decrease the inflammatory process." (PMID 17328813, 2007). "Moreover, we investigated TLR9 (rs 187084) and TLR10 (rs 11096956) gene polymorphisms and their association with asthma." (PMID 40218167, 2025). "The CC genotype of TLR9 and the GG genotype of TLR10 are associated with better asthma control." (PMID 40218167, 2025). "A study investigating the potential of TLR9 agonists adsorbed to alum adjuvants in preventing asthma-like reactions induced by tropical mite extracts showed that CpG could inhibit locally or systemically activated allergic responses." (PMID 40491911, 2025). "Therefore, several new drugs targeting different TLRs (TLR3, TLR4, TLR7, TLR8, TLR9) are currently under examination for patients with asthma." (PMID 37759430, 2023). "Among these, TLR9 has a critical immunomodulatory function in certain types of asthma." (PMID 36834541, 2023). "The Th2 response observed in this HDM asthma model depended on TLR9-mediated IL-2 production." (PMID 37426425, 2023). "The identification of “positive regulation of TLR9” by Downregulated Cluster miRNAs indicates that the process of restoring Th2/Th1 imbalance in asthma may be accompanied by miRNA regulation." (PMID 36366542, 2022). "Because we found that TLR9 involved in the pathogenesis of HDM-induced asthma, we investigated whether the DNA ligand involved was derived from HDM." (PMID 33093516, 2020). "The results showed that, compared with WT mice, tlr2−/−, and tlr4−/− mice exhibited increased infiltration of leukocytes, especially asthma-related eosinophils, in alveoli, and IgE level in serum was increased significantly in tlr2−/− and tlr9−/− mice after allergic asthma establishment." (PMID 30510553, 2018). "It was shown that TLR9 stimulation efficiently controls asthma manifestations." (PMID 29867994, 2018). "For example, human eosinophils increase their adhesion molecule CD11b and IL-8 secretion upon exposure to R-837 and CpG DNA, suggesting TLR7/8 and TLR9 in human eosinophil could be responsible for asthma exacerbation by viral infections." (PMID 29867994, 2018).
asthma (continued). "We evaluated whether post-bronchiolitis asthma was associated with polymorphisms in the TLR3 rs3775291, TLR4 rs4986790, TLR7 rs179008, TLR8 rs2407992, TLR9 rs187084, and TLR10 rs4129009 genes." (PMID 28592890, 2017). "The role of TLR9 agonists in asthma requires further evaluation." (PMID 27274620, 2016). "Polymorphism in TLR-4 is related to asthma and it is proposed that the other TLRs (e.g. TLR-9 and -3) present the similar polymorphic associations with other environmental stimuli, such as CpG methylation of TLR-9 and double-stranded RNA (dsRNA) for TLR-3." (PMID 27658857, 2016). "In addition, TLR7 senses single-stranded viral RNA which inhibits Th2 immune responses and eosinophilic asthma, and TLR9 detects unmethylated CpG motifs in microbial DNA molecules in the development of asthma and asthma exacerbation." (PMID 27274620, 2016). "Despite an association with asthma, expression of five TLR9 SNPs, including TLR9(T1237C), failed to correlate with clinical atopy." (PMID 26361369, 2015). "Nevertheless, the strongest suppressive effects were found when the TLR9 agonist was used suggesting that TLR9 agonists may also be effective in treating steroid insensitive severe asthma patients." (PMID 24618687, 2014). "TLR2, TLR6, TLR9, and TLR10 have been associated with asthma in several studies." (PMID 23496969, 2013). "Agonists of intracellular TLRs such as TLR3 agonist poly(I:C) and TLR7/8 agonist imidazoquinoline promote activation of Th1 immune responses; the TLR9 synthetic agonists are being investigated for cancer immunotherapy, asthma and allergy therapy, and vaccine adjuvants." (PMID 23151919, 2012). "Evidence from prior studies suggests that this SNP in TLR9 could be important in asthma and other inflammatory diseases." (PMID 21324137, 2011). "Although rs5743836 confers regulatory effects on TLR9 transcription, this variant does not appear to be an important asthma-susceptibility locus." (PMID 21324137, 2011). "TLR9 activation can down-regulate allergic responses by promoting Th1 cytokine generation and synthetic TLR9 agonists have been developed as new drugs to treat asthma." (PMID 21364926, 2011). "Finally, in a multi-centre asthma study, TLR4 and TLR9 were both associated with wheezing and TLR4 was also associated with allergen specific IgE secretion." (PMID 21108806, 2010). "Interestingly, in a mouse model of asthma, oral treatment with probiotic organisms inhibited the allergic response in a TLR9 dependent manner." (PMID 18315834, 2008). "Furthermore, the relationship between IL-17 and asthma has been reported in TLR other than TLR9." (PMID 33093516, 2020). "Finally, we examined whether the TLR9 response was involved in not only HDM-induced asthma but also OVA-alum-induced asthma." (PMID 33093516, 2020). "The present study was carried out to complement this exploratory study series by evaluating whether the TLR3 rs3775291, TLR4 rs4986790, TLR7 rs179008, TLR8 rs2407992, TLR9 rs187084, and TLR10 rs4129009 polymorphisms are associated with post-bronchiolitis asthma." (PMID 28592890, 2017). "Additionally, the ligand for TLR9 (CpG) is being investigated in animal models and some human studies as an adjuvant for immunotherapy of allergic diseases including allergic rhinitis and asthma." (PMID 21324137, 2011). "In an experimental asthma model using HDM extracts, the airway hyperresponsiveness of TLR9-KO mice improved compared to the WT mice, which was accompanied by a reduction of the mRNA levels of the Th2 cytokines IL-13, IL-5, and IL-4 in the lungs." (PMID 37426425, 2023). "il-10, il-4, il-13, il-17a, il-2, tlr4, tlr9, ccl2, csf2, and vegfα are top 10 hub nodes in the PPI network, so we inquired the expression profiles of these genes in asthma from the GEO database." (PMID 33133221, 2020). "Taken together our novel severe asthma model shows a very strong remodeling phenotype which is steroid insensitive and only partially sensitive to TLR7 and TLR9 agonist treatment." (PMID 24618687, 2014).
asthma (continued). "In conclusion we have developed a severe asthma model, which is steroid resistant and only partially sensitive to TLR7 and TLR9 agonist treatment." (PMID 24618687, 2014). "A TLR9 agonist, IMO-2134 (also known as QAX-935), is a lead compound for asthma and allergy indications." (PMID 23151919, 2012). "The expression levels of FCER1A and TLR‐9 in IL‐5‐ or IL‐17‐activated eosinophils and those of aryl hydrocarbon receptor and TLR‐7 in IL‐5‐activated eosinophils were significantly higher for patients with asthma than for normal individuals." (PMID 39575691, 2024). "Recently, TLR9 agonists have been proposed as a treatment option for glioblastoma (CpG oligonucleotide) or asthma, but the phase 2 clinical trials concluded with no additional benefit for patients." (PMID 31089331, 2019). "Again, intake of active vitD3 by asthma patients led to an increased expression of TLR9 but not other TLRs by IL-10 secreting CD4+ T cells." (PMID 27506771, 2016). "A relationship neither existed for TLR4 rs4986790 or TLR9 rs352140 with asthma when dust or area (rural/urban) was taken into account." (PMID 23496969, 2013). "Therefore, TLR9 and TLR10 have a role in asthma control and cardiac dysfunction." (PMID 40218167, 2025). "However, these agents have not yet achieved significant clinical success, as exemplified by a recent study of a TLR9 agonist that failed to improve asthma control." (PMID 36105216, 2022).
rheumatoid arthritis (43 papers, 2008 to 2025). A chronic, systemic autoimmune disorder characterized by inflammation in the synovial membranes and articular surfaces. "The mechanisms underlying the effects of Toll‐like receptor 9 (TLR9) and autophagy on rheumatoid arthritis (RA)‐aggravated periodontitis are unclear." (PMID 31737959, 2020). "The other TLR9 variants have also been found to be risk factors of atopic eczema, tuberculosis, Helicobacter pylori-induced gastritis, and rheumatoid arthritis." (PMID 22714906, 2012). "DNase II-deficient mice failed to digest DNA from engulfed nuclei of erythroblasts in hepatic macrophages and resulted in the robust production of type I IFN and inflammatory cytokines, which caused severe anemia and rheumatoid arthritis (RA)-like symptoms in a TLR9-independent manner." (PMID 26344113, 2013). "It was also indicated that ecDNA can significantly increase TLR9-MyD88-NF-kB signaling in the plasma of people with rheumatoid arthritis (RA), leading to the release of pro-inflammatory cytokines." (PMID 35614494, 2022). "Toll-like receptor (TLR)-4 and TLR9 are known to play important roles in the immune system, and several studies have shown their association with the development of rheumatoid arthritis (RA) and regulation of tumor necrosis factor alpha (TNF-α)." (PMID 34635730, 2021). "Another TLR9 polymorphism in the promoter region, 1486C/T (rs187084) has been associated with diseases like SLE, rheumatoid arthritis, HPV infection, pulmonary tuberculosis and certain cancers." (PMID 30651082, 2019). "Disease associations of TLR9 with SLE, type 1 DM, multiple sclerosis, inflammatory bowel disease, and rheumatoid arthritis have been reported." (PMID 28912808, 2017). "TLR-9 rs187084 polymorphism is associated weakly with SLE risk, but significantly with the risk of rheumatoid arthritis or OA." (PMID 28916728, 2017). "TLR9 is constitutively expressed on B cells that are critical in the pathogenesis of rheumatoid arthritis." (PMID 19956648, 2009). "It is becoming clear that TLRs are involved in systemic autoimmune disorders, because it was recently demonstrated TLR2 and TLR4 are involved in rheumatoid arthritis (RA) and TLR9 in systemic lupus erythematosus." (PMID 18234118, 2008). "We show that inhibiting TLR9 limits the exacerbation of arthritis induced by EBV DNA in a CIA mouse model, suggesting that TLR9 could be a potential therapeutic target for rheumatoid arthritis management in EBV-infected individuals." (PMID 38731877, 2024). "In patients with rheumatoid arthritis (RA), an increase in TLR9 levels was detected in monocyte subgroups of the circulatory system and synovium." (PMID 37139337, 2023). "A recent study showed that some enzoxazole derivatives act as TLR9 inhibitors with moderate to excellent activity in short term suppression of IL-6, suppression of IL-6 release from lymph nodes, indicating their potential as therapeutic agents for rheumatoid arthritis." (PMID 35566047, 2022). "In patients with rheumatoid arthritis (RA), neutrophil extracellular traps (NETs) induced hyperalgesia by acting on Toll-like receptors (TLR-4 and TLR-9), and the production of NETs was positively correlated with the degree of pain." (PMID 35859655, 2022). "Although there are lacking studies confirming the role of TLR9 rs5743836 in SpA, there are studies that have previously associated the rs5743836∗C to the development of rheumatoid arthritis (RA) in women." (PMID 31781672, 2019). "For this purpose, we assessed the TLR7- and TLR9-mediated IFN-α production by pDCs in SLE patients and compared the finding with those in rheumatoid arthritis (RA) patients and healthy controls." (PMID 30210502, 2018). "Our results show that rheumatoid arthritis synovial fibroblasts (RASF) express a series of TLRs, including TLR2, TLR3, TLR4, and TLR9, with the predominant expression of TLR3." (PMID 24936783, 2014).
rheumatoid arthritis (continued). "Hence, the abnormal stimulation of TLR7 and TLR9 contributes to the pathology of autoimmune diseases such as SLE and rheumatoid arthritis (RA)." (PMID 34884569, 2021). "Although the direct effect on TLR9 cleavage is not displayed, cathepsin K inhibitor inhibits TLR9 response and attenuates experimental rheumatoid arthritis in mouse model." (PMID 29997629, 2018). "Thus, hepatic macrophages in DNase II-deficient mice failed to digest DNA from engulfed nuclei of erythroblasts and exhibited robust production of type I IFN, which resulted in severe anemia and development of rheumatoid arthritis (RA)-like symptoms in a TLR9-independent manner." (PMID 23734163, 2013). "Among them, IMO-3100, a TLR7/9 dual antagonist of TLR7 and TLR9 can block the expression of IFN-β, TNF-α, and interleukin 17 (IL-17) and attenuate SLE, rheumatoid arthritis (RA) in a murine model." (PMID 36677692, 2023). "Importantly, cfDNAs extracted from blood of myocardial infarction and rheumatoid arthritis patients stimulate the expression of DNA sensor toll-like receptor 9 (TLR9) in MSCs, while an exposure to gDNA did not influence TLR9 levels." (PMID 23533696, 2013).